PIN1 (peptidylprolyl cis/trans isomerase, NIMA-interacting 1)
Diseases named in the same sentence as PIN1 in open-access papers (continued):
Sharing a sentence is not in itself a finding about the gene and the disease.
tumor (continued). "Other Pin1‐mediated mechanisms have been discovered in other tumour types." (PMID 32347623, 2020). "PIN1 also supports increased cell proliferation by promoting glycolysis in tumor cells." (PMID 32655497, 2020). "Pin1 also reduces the stability of tumor suppressive transcription factors." (PMID 32266261, 2020). "Similarly, the subsequent transwell assay indicated that silencing IL‐18 reversed the tumour‐promoting effect of Pin1 in cell migration and invasion." (PMID 32347623, 2020). "(i) IRAK1 and PIN1 are both sufficient to force R-RT in otherwise radiosensitive tumor cells." (PMID 31799178, 2019). "Notably, PIN1 overexpression did not otherwise correlate with metastatic potential, arguing against the notion that PIN1 levels merely reflected an aggressive tumor subtype." (PMID 31799178, 2019). "Consequently, treatment of API-1 in HCC cells results in reduction of cell proliferation and suppression of xenograft tumor growth through restoration of PIN1-impaired miRNA biosynthesis." (PMID 32010690, 2019). "Nevertheless, given that tumor progression depends on oxidative stress, the question arises as to whether PIN1 pro-oxidant activity could foster tumor growth and aggressiveness." (PMID 30873382, 2019). "Thus, comparing the genomes of transforming (i.e., Theileria) and non-transforming (i.e., Toxoplasma) parasites proved a valid strategy for the identification of Pin1 as a protein relevant in cell transformation and tumor growth." (PMID 31157221, 2019). "All these data clearly show that PIN1 levels and activity are regulated at several levels that can be deranged during oncogenesis and in turn have positive repercussions on oncogenic signaling and tumor phenotypes." (PMID 30873382, 2019). "Notably, ATRA also induced AQP9 expression and cooperated with ATO to induce Pin1 degradation, destabilization of Pin1’s substrate oncoproteins, and stabilization of Pin1’s substrate tumor suppressors, in both TNBC cell orthotopic and PDOX tumors." (PMID 30093655, 2018). "Research indicated that Pin1 is guilty for the inactivation of numerous tumor suppressors." (PMID 30158600, 2018). "Given the striking anticancer effects of ATO and ATRA in vitro, a critical question is whether they have any cooperative effects on Pin1 levels, Pin1-regulated oncogenic pathways, and tumor growth of TNBC in vivo." (PMID 30093655, 2018). "Indeed, ATO and ATRA together displayed cooperative effects leading to potent ablation of Pin1, inhibition of multiple oncogenic pathways, and inhibition of cell and tumor growth in vitro and in vivo." (PMID 30093655, 2018). "Moreover, Pin1 is highly enriched in breast TICs/CSCs to drive their self-renewal and tumor initiation." (PMID 30093655, 2018). "Importantly, ATO and ATRA co-treatment not only effectively reduced breast TIC frequency by ~90-fold (P < 0.0001), but also dramatically reduced tumor growth, similar to Pin1 KO." (PMID 30093655, 2018). "Moreover, ATRA also synergistically enhanced the ability of sorafenib to reduce Pin1 and inhibit tumor growth of HCC in mouse xenograft models." (PMID 28404959, 2017). "Our results, therefore, suggested miR-874-3p to be a clinically and pathologically relevant negative regulator of PIN1, and might potentially play a tumour suppressive role in HCC." (PMID 28076852, 2017). "Moreover, miR-140-5p decreased tumor growth of HCC by ablating Pin1 and its downstream target cyclin D1 in vivo." (PMID 28383568, 2017).
tumor (continued). "In this study, the authors identify a covalent inhibitor of PIN1 with anti-tumour and anti-metastatic properties thanks to PIN1 inactivation and to the release, after binding to PIN1, of a quinone-mimicking compound that elicits reactive oxygen generation and causes DNA damage." (PMID 28598431, 2017). "In addition, to further validate the role of PIN1 in miR-874-3p mediated tumour suppressive function, miR-874-3p was over-expressed in PIN1-silenced cells (PLC/PRF/5 with PIN1 knocked-down by siRNA)." (PMID 28076852, 2017). "Furthermore, these tumour suppressive functions conferred by miR-874-3p were abrogated by over-expression of PIN1." (PMID 28076852, 2017). "Moreover, Pin1 was shown to reduce proliferation in vitro and tumor growth in a xenograft model using renal cell carcinoma cell lines." (PMID 28426725, 2017). "The contradictory role of Pin1 in oncogenesis suggests that Pin1 could act as a tumor promoter or conditional tumor suppressor depending on the Pin1 expression level, cell types and the signal transduction process that is regulated." (PMID 27658202, 2016). "The inhibition of PIN1 suppressed tumor growth in vitro and in vivo." (PMID 27258148, 2016). "Together with the current findings, the lack of or inadequate proteasomal degradation may be a potential mechanism in explaining PIN1 accumulation in EBV-associated NPC, which subsequently aids tumor cell survival." (PMID 27258148, 2016). "Pin1 has been reported that it contributed to tumor development and promoted tumor aggressiveness." (PMID 27008710, 2016). "In this system, 49 credits were assigned to poor pathological grading, 33 to reduced expression of TGFBR2, 45 to over-expression of TGF-β, 32 to over-expression of MAPK, 100 to over-expression of pin1, 50 to over-expression in tumor tissue and 22 to reduced expression of TGF-β in normal mucosa." (PMID 27008710, 2016). "Indeed, Pin1 activates numerous oncogenes or growth enhancers and also inactivates a large number of tumor suppressors or growth inhibitors." (PMID 26039047, 2015). "Pin1 levels have been clearly demonstrated to correlate with tumor grade." (PMID 24357640, 2014). "Higher Pin1 mRNA level in tumor was identified in 26 (62%) patients." (PMID 25160749, 2014). "The tumor size from cells with Pin1 knockdown was smaller than that from parental CE81T cells." (PMID 25160749, 2014). "Finally, Pin1 appears to play important roles both in oncogenic and tumor suppressive signaling pathways." (PMID 24982848, 2014). "Conversely, Pin1 overexpression bypassed the tumor suppressor function of Fbxw7α, as demonstrated by tumors co-expressing both proteins, that displayed increased volume, rescued N1-ICD levels, its transcriptional activity on target genes as well as the levels of mesenchymal markers." (PMID 24357640, 2014). "Functionally, we show that Fbxw7α acts as an essential negative regulator of breast CSCs' expansion by restraining Notch activity, but the establishment of a Notch/Pin1 active circuitry opposes this effect, thus promoting breast CSCs self-renewal, tumor growth and metastasis in vivo." (PMID 24357640, 2014). "We also investigated the Pin1 level in 89 primary ESCC tumor samples by IHC." (PMID 25160749, 2014). "However, further studies are warranted to examine the mechanisms by which the role of PIN1 in the invasion and metastasis of the tumor is promoted." (PMID 24179535, 2013). "However, why Pin1 facilitates ubiquitin-mediated degradation of tumor suppressors but also stabilizes Nanog, a novel oncogene, by suppressing its ubiquitination has yet to be fully clarified and requires further research." (PMID 23708493, 2013).
tumor (continued). "The finding that Pin1 is less oxidized in tumor tissue compared with dysplasia may further correlate with the ability of tumor cells to withstand high levels of ROS by protecting several cellular component from oxidative insult." (PMID 22470562, 2012). "The assay, described in this paper, was based on the determination of a ΔΔCT value (ΔΔCT method) for each sample (the greater was the ΔΔCT value, the lower was the expression of PIN1 gene) and on calculating the difference in PIN1 expression level between tumour sample and calibrator (RQ value)." (PMID 21219594, 2011). "Pin1 is a pivotal regulator of cyclin D1 expression, and disruption of the cyclin D1 gene in mice also suppresses the ability of the c-Neu transgene to induce tumor development in the mammary gland." (PMID 19077306, 2008). "Knowing which tumors express Pin1 highly and therefore are "Pin1-inhibitor-sensitive" may help assess, which tumor types might respond to Pin1-directed treatments." (PMID 19077306, 2008). "Likewise, Pin1 levels in tumor tissues were detected via western blotting." (PMID 41322199, 2025). "This led to the hypothesis that Pin1 may also act as a tumor suppressor." (PMID 38745861, 2024). "Thus, the combination of PIN1- and CDK4-inhibitors achieves synergistic anti-tumor activity against Rb-proficient or -deficient TNBC in immune-compromised or -competent mice, with an excellent safety profile, making it a strong candidate for clinical development." (PMID 38622115, 2024). "In addition, PIN1 may execute the oncogenic role through promoting the degradation or inactivation of tumor suppressors such as PML and FBXW7." (PMID 36813923, 2023). "We next investigated whether the tumor promoting function of PIN1 in TNBC is mediated by pVHL." (PMID 36813923, 2023). "Furthermore, because cis-ATR has antiapoptotic properties, we surmise that it may have an oncogenic role, whereas Pin1 may have tumor-suppressive properties in relation to ATR’s anti-apoptotic activity at the mitochondria." (PMID 37511442, 2023). "However, chemical inhibitors of Pin1 might be potential therapeutic agents that target both tumor-initiating and non-tumor-initiating cells." (PMID 35433695, 2022). "An increasing body of evidence has shown that Pin1 promotes tumor initiation, development, and resistance to cell death as well as enabling replicative immortality by upregulating oncogenes and proliferating-promoting factors or downregulating tumor suppressors and proliferation-suppressing factors." (PMID 33807199, 2021). "In a previous study, we have reported that Pin1 interacts with Fbw7 in a phosphorylation-dependent manner and promotes Fbw7 self-ubiquitination and protein degradation, indicating that Fbw7 protein destruction and tumor suppressor function are negatively regulated by Pin113." (PMID 30783083, 2019). "Thus, inducible Pin1 downregulation suppressed tumor growth in AML xenograft model in vivo." (PMID 29848341, 2018). "To demonstrate that miR-140-5p could inhibit HCC tumor growth by targeting Pin1 in vivo, we subcutaneously injected stable miR-140-5p- or miR-NC (negative control)-expressing Huh7 cells into the either flank of the same nude mice, followed by monitoring tumor growth for 8 weeks after implantation." (PMID 28383568, 2017). "The overexpression of PIN1 might enhance tumor cell growth via the upregulation of cyclinD1." (PMID 27258148, 2016). "Furthermore, Pin1 depletion in athymic mice inhibits both tumor growth and angiogenesis." (PMID 26039047, 2015). "Whether PIN1 acts as a tumor promoter or suppressor remains a controversial issue." (PMID 24179535, 2013).
tumor (continued). "Paired tumor and peritumor tissues from 211 patients with HCC were analyzed to correlate SENP1, OCT4, SNAIL, PIN1, and TWIST expression with overall survival (OS) and disease-free survival (DFS) using a Kaplan-Meier survival analysis." (PMID 41438340, 2026). "To investigate PIN1 expression in scRNA-seq data, we analyzed the GSE178341 dataset comprising 371,223 tumor and adjacent normal cells from treatment-naïve CRC patients classified as MSS or MSI-H." (PMID 41246306, 2025). "Using human tumor tissue samples, MSS CRC cells, and animal models, we systematically evaluated the role of Pin1 as a mediator of CRC immunotherapy resistance, with a specific focus on its ability to regulate the TME." (PMID 41246306, 2025). "The effectiveness of combined AMPNs and anti-PD-1 treatmentwas also supported by tumor weight data and tissue staining of thesemice at sacrifice and corresponded with TME Pin1 inhibition and TIMEchanges (Figures 8Dand S40C,D)." (PMID 39051165, 2024). "The combined inhibition of CDK1 and Pin1 using RO3306 and sulfopin has been shown to suppress orthotopic tumor growth." (PMID 39624096, 2024). "Similar results were also observedwhen final tumor weights were observed in these mice and corresponded with tissuestaining and TME Pin1 inhibition." (PMID 39051165, 2024). "Combined inhibition of Pin1 and CDK1 with sulfopin and RO3306 most effectively suppresses orthotopic tumor growth." (PMID 38167292, 2024). "The interaction between Pin1 and TIS21, a tumor suppressor that is highly expressed in normal proximal tubules of the kidney but is lost in RCC, leads to cell death." (PMID 38711994, 2024). "Here, the authors reveal that a reciprocal inhibition of PIN1-APC/CCDH1 controls the cell cycle and mitotic protein degradation, offering a synergistic anti-tumor strategy." (PMID 38622115, 2024). "Peptidyl-prolyl cis-trans isomerase NIMA-interacting 1 (PIN1) contributes to the upregulation of cyclin D1, either directly or via the abnormal accumulation of β-catenin in tumor cells." (PMID 37427143, 2023). "To further investigate the role of Pin1 in hela cell EMT in vivo, we used the Pin1 inhibitor Juglone to treat xenograft tumor." (PMID 36684109, 2023). "PIN1 and CDK1 cooperatively modulate the protein turnover of pVHL, thereby conferring tumor growth, chemotherapeutic resistance and metastasis both in vitro and in vivo." (PMID 36813923, 2023). "Our results demonstrated that PIN1 and CDK1 cooperatively destabilize pVHL, thereby promoting tumor progression of TNBC." (PMID 36813923, 2023). "ATO’s capability to block tumor proliferation was positively related with Pin1 degradation and AQP9 presence and Pin1 degradation." (PMID 36077720, 2022). "Our current data show that two potent chemical Pin1 inhibitors, Juglone and KPT6566, induce apoptotic cell death and inhibit the tumorigenicity of CD44+CD133+ tumor-initiating Caco-2 CRC cells." (PMID 35433695, 2022). "Previous study also documented that Pin1 inhibition using small molecule inhibitor such as ATRA or short hairpin RNA, reduces tumor growth via inhibiting PI3K/AKT signaling pathways." (PMID 34805153, 2021). "We performed immunohistochemistry analyses on the xenograft tumour tissues to examine the expression of Pin1, with the results showing that KPT-6566 significantly reduced Pin1 expression in these tissues." (PMID 32010480, 2020). "Pin1 overexpression increased the Gli1 protein level, a regulator of the EMT, by increasing the protein stability of Gli1, and promotes EMT and tumor cell motility." (PMID 33162791, 2020). "PIN1 is inhibited by BRCA-1, the tumor suppressor gene suggesting that PIN1 would play an important role in the development of tumors in which BRCA1 is mutated." (PMID 32655497, 2020).
tumor (continued). "For example, in pancreas cancer, elevated levels of PIN1 were shown to cooperate with MYC and NRF2 to maintain redox balance, allowing for tumor cell proliferation and survival." (PMID 32300594, 2020). "Due to its PIN1-inhibitory activity, API-1 has been found to increase XPO5-mediated pre-miRNA export from the nucleus to the cytoplasm and restore biosynthesis of tumor suppressive miRNAs in HCC cells." (PMID 32010690, 2019). "Interestingly, higher Pin1 and RhoC expression were significantly associated with smaller tumor, and high RhoA also demonstrated such trend, which might be due to dissemination of HCC cells from the primary tumor." (PMID 31324164, 2019). "EGCG binding to membrane receptors, such as TGFR-II, intracellular molecules, such as Pin1 and secreted enzymes, such as MMPs, provided noteworthy information about the mechanisms of EGCG-mediated tumour suppression." (PMID 30563268, 2018). "We have demonstrated that PIN1 is over-expressed in over 50% of HCC and its over-expression leads to β-catenin and cyclin D1 accumulation in tumour cells." (PMID 28076852, 2017). "The expressions of PIN1, miR-296-5p and miR-874-3p in HCC were further quantified in tumour samples and compared with their paired NT." (PMID 28076852, 2017). "Consequently, dysregulation of PIN1 may result in tumour development." (PMID 28076852, 2017). "Pin1 overexpression in human HCC is an independent factor for poor prognosis, correlating with larger tumor size and increased portal vein invasion in HCC48." (PMID 28383568, 2017). "Since PIN1 transcription is similar in both NPC and normal NP cells, the PIN overexpression in the tumor cells is regulated by post-transcriptional mechanisms." (PMID 27258148, 2016). "This study demonstrates the oncogenic role of PIN1 in NPC tumorigenesis, and shows that its overexpression can enhance tumor cell growth via the upregulation of cyclinD1." (PMID 27258148, 2016). "Regarding the tumorigenic properties of PIN1, we evaluated the effects of the PIN1 inhibitor Juglone on NPC tumor cell growth, apoptosis and in vivo tumor development." (PMID 27258148, 2016). "The significant direct correlation observed between Pin1 and Notch3 expression levels in human T-ALL cell lines and primary tumor samples confirms the possible relevance of our observations for human T-ALL development." (PMID 26876201, 2016). "Despite this marked difference in gene regulations, Pin1 siRNA and Juglone exert a strong inhibitory effect on both the LNCaP and the DU145 cell line, suppressing in vitro cell proliferation as well as tumor enlargement when transplanted into mice." (PMID 26039047, 2015). "Positive PIN1 expression was observed in 35 of the 67 (52.2%) ECC cases and was predominantly localized to the nucleus of the tumor cells." (PMID 24179535, 2013). "PIN1 is able to promote the degradation of c-Myc and cyclin E with the mediation of the FBXW7 E3 ligase, thus providing the evidence that it acts as a tumor suppressor." (PMID 24179535, 2013). "We assessed Pin1 expression in CRC cell lines and tissues, and conducted functional assays, in vitro co-cultures, and in vivo studies (using a Pin1 inhibitor and anti-PD-1 in CT26 subcutaneous tumor and liver metastasis mouse models) to evaluate its effects and mechanisms." (PMID 41246306, 2025). "Moreover, silencing METTL3 reduces PIN1 overexpression-induced colony formation in MCF7 cells and enhances tumor growth in 4T1 cells in mouse models." (PMID 38961497, 2024). "The prolyl isomerase PIN1 (SE = 1.1), whose overexpression in CAFs has not been fully profiled yet, plays critical roles in tumor initiation and progression." (PMID 38892190, 2024). "Treatment with the proteasome inhibitor MG132 showed negligible effects on Pin1 expression in GSCs but markedly restored Pin1 protein levels in the matched non-stem tumor cells (NSTCs)." (PMID 38167292, 2024).